ABL1 (ABL proto-oncogene 1, non-receptor tyrosine kinase)
Diseases named in the same sentence as ABL1 in open-access papers (continued):
Sharing a sentence is not in itself a finding about the gene and the disease.
chronic myeloid leukemia (continued). "Chronic myeloid leukemia (CML) and Philadelphia (Ph)-negative myeloproliferative neoplasms (MPN) are generally distinct clonal disorders, with the co-occurrence of BCR::ABL1 rearrangement with concomitant Ph-negative MPN rarely reported." (PMID 41896663, 2026). "Chronic myeloid leukemia (CML) and BCR::ABL1-negative MPN were thought to be mutually exclusive, but synchronous and sequential cases have been reported." (PMID 40906032, 2025). "Factors correlated with lower overall survival in patients with atypical chronic myelogenous leukemia, BCR/ABL1 negative." (PMID 34868917, 2021). "Atypical chronic myelogenous leukemia (aCML), BCR/ABL1 negative is a rare myelodysplastic/myeloproliferative neoplasm, usually manifested with hyperleukocytosis without monocytosis or basophilia, organomegaly, and marked dysgranulopoiesis." (PMID 34868917, 2021). "Expression of the Philadelphia chromosome (Ph), resulting from fusion of the non-receptor tyrosine kinase ABL1 on chromosome 9 with BCR on chromosome 21, is the hallmark of chronic myeloid leukemia (CML), but is also found in 20-30% of acute lymphoblastic leukemia (ALL) cases." (PMID 21299849, 2011). "The fifth edition of the WHO Classification has updated the name of atypical chronic myeloid leukemia, BCR::ABL1-negative (aCML), and replaced it with myelodysplastic syndrome/myeloproliferative neoplasms with neutrophilia (MDS/MPN with neutrophilia), while the ICC has kept the original name." (PMID 37370785, 2023). "After an initial diagnosis of chronic myeloid leukemia, the patient’s clinical course was shaped by hematologic toxicity, the emergence of treatment-resistant BCR-ABL1 clones, and the expansion of a CSF3R-mutant clone without ABL1 mutations under selective pressure from tyrosine kinase inhibitors." (PMID 33516272, 2021). "Atypical chronic myelogenous leukemia (aCML), BCR/ABL1 negative is a rare disorder classified into the category of myelodysplastic/myeloproliferative neoplasms (MDS/MPN), according to the 2016 revision of the World Health organization (WHO) classification of myeloid neoplasms and acute leukemia." (PMID 34868917, 2021). "It is important to ensure that a blast crisis of chronic myeloid leukemia with an MPAL immunophenotype, post-cytotoxic therapy leukemia with an MPAL immunophenotype, and MPAL that has acquired BCR::ABL1 secondarily is not miscategorized as de novo MPAL with BCR::ABL1 fusion." (PMID 40075717, 2025). "However, the present work found evidence that miR-7-5p may be related to chronic myeloid leukemia in a non-specific way, mainly considering its relationship with the BCR::ABL1 transcript." (PMID 38542337, 2024).
leukemia (548 papers, 2005 to 2026). A malignant (clonal) hematologic disorder, involving hematopoietic stem cells and characterized by the presence of primitive or atypical myeloid or lymphoid cells in the bone marrow and the blood. "Co-inhibition of proteasomes and histone deacetylases eliminates TKI-refractory BCR::ABL1-driven leukaemia cells by inducing mitochondrial apoptosis and loss of clonogenic potential." (PMID 41696976, 2026). "Established asciminib-resistant (ASCI-R) clones of KCL-22 cell line (n = 8) were analyzed using Next Generation Sequencing (NGS) to identify somatic mutations in SH3, SH2, and kinase (KD) domains of BCR::ABL1 and in 62 selected leukemia-associated genes." (PMID 40858806, 2025). "A further study, however, found that therapy‐related leukaemias following treatment with radiation therapy alone had higher rates of BCR::ABL1 mutations compared to MLL." (PMID 40490854, 2025). "In the present study, we introduced the T315M mutation into the intrinsic BCR::ABL1 gene in three Ph + leukemia cell lines via HR using the CRISPR/Cas9 system." (PMID 40208408, 2025). "Drug resistance to tyrosine kinase inhibitors (TKIs), due to BCR::ABL1 mutations and residual leukemia stem cells (LSCs), remains a major challenge in CML treatment." (PMID 37880985, 2024). "This advanced disease stage exhibits clonal, genomic, and molecular heterogeneity, often featuring additional chromosomal aberrations and mutations in the BCR::ABL1 kinase domain and/or other leukemia-related genes." (PMID 38615117, 2024). "We interrogated samples with BCR::ABL1‐positive ALL in several leukemia stages for ABL1 KD mutations using next generation sequencing (NGS)." (PMID 39440695, 2024). "More than 70 mutations were reported in the BCR::ABL1 kinase domain (KD) in people with BCR::ABL1‐associated leukemias." (PMID 39440695, 2024). "Common mutations found in leukemia patients, such as ABL1, FGFR1, KRAS, MET, NOTCH1, and PTPN11, were also found among our patient population, although not universally." (PMID 37092520, 2023). "For example, the T315I mutation of ABL1 in leukemia cells reduces the efficacy of imatinib, and LIGHTHOUSE accurately predicted the effect of this mutation." (PMID 36246574, 2022). "Several retrospective studies found that mutations in leukemia-associated genes in addition to BCR::ABL1 are not only a phenomenon seen in advanced or blast crisis CML but also in chronic phase CML." (PMID 35902731, 2022). "The resulting chimeric protein, BCR::ABL1, is a potent tyrosine-kinase signalling protein that drives cell proliferation and reduces apoptosis, which causes leukaemia." (PMID 35884363, 2022). "Probably the clearest indication is in drug compliant persons failing to respond to TKI-therapy and those with some BCR::ABL1 mutations, high-risk additional cytogenetic abnormalities (ACAs) and/or with other signs of leukaemia progression." (PMID 35338251, 2022). "Leukemia with ETV6/ABL1 fusions is rare and associated with a poor prognostic outcome, but are sensitive to tyrosine kinase inhibitors." (PMID 34503197, 2021). "A variety of breakpoints in BCR and ABL1 rearrangements generate BCR-ABL1 chimeric proteins with different domain compositions, of which the three major variants (p185, p210, and p230) occur in different types of leukemia." (PMID 30040819, 2018). "It is well known that the frequency of T315I mutation and/or multiple ABL1 mutations are higher in patients with long-term TKIs treatment, which is thought as the major reason for leukemia relapse." (PMID 29291008, 2017). "The diseases, leukemia and multiple myeloma, are also highly associated with the ABL1 based on our analysis." (PMID 21448266, 2011). "Under these circumstances, direct induction of the mutations into the intrinsic BCR::ABL1 gene in human leukemia cells could be another useful model system." (PMID 39872583, 2024).
leukemia (continued). "Therefore, ABL1 can exhibit dual roles by suppressing tumor growth and serving as a potential therapeutic target in leukemias with oncogenic variants of the kinase." (PMID 37627077, 2023). "In these circumstances, BCR::ABL1 could be considered a CHOP mutation likely to progress to overt leukemia subsequent to a variable latency period." (PMID 37895120, 2023). "The proto-oncogene ABL (ABL1 in humans) was first discovered from the Abelson murine leukemia virus and has been identified as an oncogene that was frequently associated with the chromosome translocations in human leukemia." (PMID 27903968, 2017). "Therefore, developing ABL1 inhibitors that target resistance mutations, and in particular the ABL1-T315I gatekeeper mutation, currently remains a goal of leukemia drug research." (PMID 23746052, 2013). "Resistance to tyrosine kinase inhibitors (TKIs) remains a major challenge in breakpoint cluster region (BCR)::Abelson 1 (ABL1)-driven leukaemias." (PMID 41696976, 2026). "BCR::ABL1 transforms normal hematopoietic stem cells (HSCs) into leukemia stem cells (LSCs), primitive leukemic cells capable of indefinite self-renewal and of initiating and maintaining the disease." (PMID 39893171, 2025). "We measured the rate at which the leukemia marker BCR::ABL1 decreased within the first three months and compared it with the long-term treatment outcome." (PMID 41463243, 2025). "The synergistic anti-leukemic effect of tyrosine kinase inhibitors combined with venetoclax has been previously demonstrated in both preclinical and clinical settings for BCR::ABL1-positive leukemias." (PMID 40858806, 2025). "They discovered that the down-regulation of ABL1 kinase activity in AML1-ETO and NUP98-PMX1 leukemias is associated with leukemia initiation and progression." (PMID 40584293, 2025). "It remains to be determined how and to which extent CDK6 inhibition alters metabolism of cancer cells and which role CDK6 specifically plays in this context in BCR::ABL1+ leukemia." (PMID 39966356, 2025). "The specificity of VTP-50469 against KMT2A-rearranged leukemia was further reinforced by its inability to significantly delay the progression of a BCR::ABL1 fusion-positive ALL PDX." (PMID 39510293, 2024). "In this study of patients with B-ALL, we show that, in the context of risk-directed therapy and the use of tyrosine kinase inhibitors (TKI) for patients with BCR::ABL1 leukemia, unfavorable subtype groups are independently prognostic." (PMID 39606455, 2024). "In human Ph+ leukemia cell lines, amplification of the BCR::ABL1 gene is generally observed, and TCCS has four alleles of the BCR::ABL1 gene." (PMID 39872583, 2024). "In our previous studies on BCR::ABL1-positive leukemias, we defined “CML-like” leukemias, diagnosed as ALL but exhibiting BCR::ABL1 fusion in multipotent, not fully leukemic progenitors, biologically resembling CML in lymphoid blast crisis." (PMID 38970095, 2024). "Previous publications on BCR::ABL1-positive leukemia have primarily focused on the Major form of the translocation due to technical challenges in determining breakpoints in the substantially larger minor BCR region (~ 2.9 vs. ~71.5 kbp)." (PMID 38970095, 2024). "Disease relapse upon BCR::ABL1 TKI treatment discontinuation or the development of treatment resistance in CML can occur due to the persistent leukemia stem/progenitor cell population." (PMID 39063200, 2024). "Two main reasons behind the persisting obstacles to treatment are the acquired mutations in the ABL1 kinase domain and the presence of quiescent CML leukemia stem cells (LSCs) in the bone marrow, both of which can confer resistance to TKI therapy." (PMID 38542279, 2024). "New evidence emphasizes the crucial role of BCR::ABL1-independent pathways, particularly the importance of leukemia stem cells that persist and sustain the disease even in the absence of BCR::ABL1 kinase activation." (PMID 38607055, 2024).
leukemia (continued). "Phospho flow cytometry and apoptosis assays were performed to assess the functional effects of monobody translocation into BCR:ABL1-expressing leukemia cells." (PMID 39415233, 2024). "For example, in CML some leukaemia cells carry a newly-mutated, resistant BCR::ABL1 fusion gene but mutated transcripts are undetectable by NGS." (PMID 38637690, 2024). "Chromosomal translocation of human ABL1 to the breakpoint cluster region (BCR) gene results in production of the BCR-ABL1 fusion protein in patients with different types of leukemias." (PMID 38190417, 2024). "CML was the first disease to have a targeted therapy, with the development of imatinib, a TKI that specifically targets the BCR::ABL1 protein in leukemia cells." (PMID 39450252, 2024). "If BCR::ABL1 is undetected (molecularly undetectable leukemia), the number of reference gene transcripts in the same volume of cDNA used to test for BCR::ABL1 indicates the sensitivity for that particular sample." (PMID 37794101, 2023). "Instead of inhibiting PARP using an inhibitor, we crossed Parp1 knockout mice with BCR/ABL1 Tg mice and examined leukemia development and death." (PMID 37165001, 2023). "In summary, NUP98-PMX1;Abl1−/− cells were highly sensitive to PI3K and mTOR inhibitors when compared to the Abl1 + /+ counterparts, and imatinib sensitized Abl1 + /+ leukemia cells to PI3K inhibitor buparlisib." (PMID 36959186, 2023). "The BCR::ABL1 fusion gene produces the BCR::ABL1 tyrosine kinase, which leads to leukemia cell proliferation." (PMID 38034530, 2023). "On one hand, the loss of ABL1 led to the increased proliferation and expansion of BCR-ABL1 murine leukemia stem cells." (PMID 37627077, 2023). "Here, a murine transplantation model yielded data supporting the potential of PARPi for the treatment of BCR/ABL1-positive leukemia." (PMID 37165001, 2023). "AMLs carrying the BCR::ABL1 rearrangement have often been described as de novo leukemias and, more rarely, as a secondary event during disease relapse." (PMID 37895120, 2023). "In vitro experiments have shown that bosutinib has antiproliferative activity against multiple BCR::ABL1-positive leukemia cell lines as well as the ability to block BCR::ABL1 phosphorylation at sub-micromolar concentrations." (PMID 38004514, 2023). "In transgenic mice of p210 or p190 BCR::ABL1 under diverse promoters, leukemia progression has been widely confirmed." (PMID 35999358, 2023). "Leukemia in BCR/ABL1 Tg mice developed 6 months after birth, after which time the mice started to die18." (PMID 37165001, 2023). "FYN is a major downstream target of ABL1 in human leukemias and LYN signaling promotes resistance to ABL1 inhibitors." (PMID 38047771, 2023). "In fact, compound 55 demonstrated activity against Abl1 and T315I mutant Abl1 leukemia cells, with IC50 values of 0.87 and 9.4 μM, respectively." (PMID 38069175, 2023). "We will also evaluate the current evidence for treatment of BCR::ABL1-positive leukaemias, including TKI discontinuation in optimally responding CP-CML patients." (PMID 38550948, 2023). "Here we show that ABL1 kinase inhibitor imatinib can be applied to increase the anti-leukemia effect of DNA damage response inhibitors (DNA-PKi and ATRi) and intracellular signaling inhibitors (PI3Ki) in AML1-ETO and/or NUP98-PMX1 leukemia cells." (PMID 36959186, 2023). "Our knowledge of BCR::ABL1-positive leukaemias continues to evolve and with this, a personalised approach to leukaemia management continues to expand." (PMID 38550948, 2023). "Death from BCR/ABL1-mediated leukemia was observed in sham-treated mice at 1 month post-transplantation." (PMID 37165001, 2023). "In fact, it represents one species of activated ABL1 with a central role in a number of leukemias such as a subset of Ph-like cALL, T-ALL and others together with that in Ph-MPN." (PMID 35941390, 2022). "Treatment with ABL1 inhibitor imatinib mesylate revealed as a highly effective targeted therapy against the leukemia driving protein kinase." (PMID 36172171, 2022).
leukemia (continued). "TAA/ABL1 ratios exceeded the healthy threshold in 84% (16/19) of these patients with active leukemia after HCT." (PMID 36248870, 2022). "TKIs used for the treatment of Ph + leukemia such as dasatinib are dual ABL1/SFK inhibitors that combine in one compound the inhibition of two kinases shown to be indispensable for the growth of FKH1 cells." (PMID 35941390, 2022). "PB leukemia cells (GFP+B220+) for the recipient mice was monitored on days 15, 18, 22, 25 and 29 post BMT, the percentage and total number of leukemia cells was significantly lower in BCR/ABL1-Rora group recipients." (PMID 35414788, 2022). "ABL1 is primarily known as a leukemia-related oncogene due to translocation, but about 2.2% of ABL1 mutations have been identified in bladder cancer, and high expression in solid cancer has also been detected." (PMID 33952249, 2021). "The introduction of ABL1-directed TKIs has dramatically improved the hematological, cytogenetic and molecular responses of leukemia patients displaying a BCR-ABL1 chimeric fusion." (PMID 34276365, 2021). "BCR/ABL1 (Philadelphia chromosome)-like ALL was initially identified as a subgroup of leukemias with a leukemic cell gene expression profile similar to that of BCR/ABL1-positive ALL and frequent IKZF1 alterations but without the BCR/ABL1 fusion." (PMID 33946897, 2021). "It was later discovered that constitutive activation of ABL1 upon fusion with the breakpoint cluster region (BCR) generated the BCR-ABL1 oncoprotein responsible for driving several forms of human leukemia." (PMID 34022881, 2021). "BCR/ABL1 transduced bone marrow gives rise to various lineages of malignancies including, B lineage, myeloid and mixed lineage leukemias." (PMID 34484175, 2021). "All NOTCH1-signaling-dependent T-ALL cell lines were sensitive to MRK-560 and its combination with ruxolitinib or imatinib in JAK1- or ABL1-dependent cell lines synergistically inhibited leukemia proliferation." (PMID 34167562, 2021). "In multiple myeloma (MM) and leukemias, YAP appears to have a tumor-suppressive effect by controlling the Abl1-dependent DNA damage response, which causes programmed cell death in tumor cells." (PMID 33924049, 2021). "At least one normal ABL1 allele is usually present in cells expressing BCR-ABL1, acting as a tumor suppressor, as its knockout in CML CP cells leads to increased survival of cells in vitro and development of much more aggressive leukemia in mice." (PMID 32806528, 2020). "ABL class fusion: Kinases that are altered in this subtype of Ph-like ALL are Abelson murine leukemia one (ABL1), ABL2, colony-stimulating factor one receptor (CSF1R), platelet-derived growth factor receptor A (PDGFRA), and PDGFRB." (PMID 33133861, 2020). "Fusion of ABL1 to BCR/TEL/NUP214 is observed in a large number of leukemia patients and allosteric stimulation of the normal ABL1 kinase activity enhanced the antileukemia effect of ABL1 tyrosine kinase inhibitors." (PMID 31537905, 2020). "Another important molecular target that is widely exploited in the design of drugs suitable for leukemia is proto-oncogenic kinase ABL1." (PMID 32110969, 2020). "Results show that migration is inhibited by siRNA, demonstrating that ABL1 is required for CXCR4-mediated leukemia cell migration toward CXCL12." (PMID 32903764, 2020). "Within the B-ALL molecular subtypes, IL7R expression values were higher in the BCR/ABL1, ETV6/RUNX1, TCF3/PBX1, and KMT2A(MLL) high-risk leukemia subtypes." (PMID 32085659, 2020). "NF-κB1 and STAT3 were the main factors involved in cytokine release, and both NF-κB1 and STAT3 were proven to be downstream targets of ABL1 in leukemia." (PMID 31396300, 2019).